PAK2 (p21 (RAC1) activated kinase 2)
Diseases named in the same sentence as PAK2 in open-access papers (continued):
Sharing a sentence is not in itself a finding about the gene and the disease.
pancreatic cancer (continued). "Finally, in single-cell sequencing of pancreatic cancer cells, a comparison of PAK2 expression revealed a significantly higher level of PAK2 in pancreatic cancer cells from liver metastatic tissues compared to primary pancreatic cancer tissues." (PMID 38343537, 2024). "In our proposed temporal sequence analysis, we observed that PAK2 tends to induce cancer cells into a state of lower differentiation, representing a crucial mechanism contributing to the facilitation of liver metastasis in pancreatic cancer." (PMID 38343537, 2024). "Existing evidence described that PAK2 promoted the growth and metastasis of pancreatic cancer." (PMID 39208654, 2024). "Therefore, we believe that the promotion of PAK2 in pancreatic cancer liver metastasis is specific." (PMID 38343537, 2024). "GSVA suggests a strong connection between the overexpression of PAK2 and the activation of the TGF-beta signaling pathway in pancreatic cancer." (PMID 38343537, 2024). "Interestingly, in pancreatic cancer, PAK4 exhibited the highest frequency of alterations (10%), a notable increase compared to PAK2 (4%) and PAK3 (1%), while PAK1, PAK5, and PAK6 were altered in fewer than 1% of cases." (PMID 39756822, 2025). "Furthermore, to obtain a sufficient number of pancreatic cancer cells, we integrated two datasets, GSE155698 and GSE154778, extracted cancer cells, and divided them into low and high PAK2 expression groups." (PMID 38343537, 2024). "Examination of proliferation post-PAK2 knockdown using CCK8 showcased diminished OD values in comparison to the control group, indicative of PAK2 knockdown hindering the proliferation of pancreatic cancer cell lines PANC-1 and Bx-PC-3." (PMID 38343537, 2024). "After analyzing other single-cell data, we found that PAK2 has no significant promoting effect on the lung and vaginal metastasis of pancreatic cancer." (PMID 38343537, 2024). "Furthermore, because PAK2 and PAK4 have been related to pancreatic cancer, these two p21-activated kinases could be considered a prognostic and immunotherapeutic marker pancreatic cancer; therefore, future research in this direction should be necessary." (PMID 40001881, 2025). "Moreover, examination of the GSE71729 dataset indicated a notable elevation in PAK2 gene expression levels among patients with pancreatic cancer and liver metastasis, as opposed to those without liver metastasis." (PMID 38343537, 2024).
hepatocellular carcinoma (8 papers, 2014 to 2025). A malignant tumor that arises from hepatocytes. "Pak2 has also been implicated in the migration of hepatocellular carcinoma cells and monocytes." (PMID 25050916, 2014). "In addition, CCHE1 inhibited miR‐922, which, in turn, leads to an incline in PAK2 and participates in tumorigenesis of oral squamous cell carcinoma development, and miR-26a halted cancer invasion by restricting PAK2 in hepatocellular carcinomas." (PMID 35087589, 2022). "TGF-β treatment induced hepatoma cell migration via phosphorylation of AKT and PAK2, while treatment of AKT inhibitor inhibited PAK2 phosphorylation, indicating PAK2 as a downstream mediator of TGF-β and AKT signaling." (PMID 25093037, 2014). "For instance, the results with PAK2 inhibitor could not be reproduced in the hepatocellular carcinoma (HCC) cell line Huh6 or in HCC organoids, indicating that this pathway may be specifically relevant in starved HepG2 cells." (PMID 35635656, 2022).
lung carcinoma (8 papers, 2013 to 2025). "P21-activated kinase 2 (PAK2) - mediated activation of β-catenin pathway enhances lung cancer cell stemness and osimertinib resistance." (PMID 40959099, 2025). "In lung cancer, PAK2 had the highest incidence of alterations (12%), significantly higher than any other PAK isoforms, which ranged from 0.6% to 3%." (PMID 39756822, 2025). "The roles of PAK1 and PAK2 were analyzed in detail using siRNAs in a lung carcinoma model." (PMID 31748572, 2019). "Among PAKs, PAK1, PAK2, and PAK4 exhibit a higher expression level in most cancer types; PAK1 and PAK4 are the most studied and better characterized, yet PAK2 has the highest alteration frequency among all PAKs, especially in lung cancer." (PMID 36429067, 2022).
colorectal cancer (7 papers, 2019 to 2024). A primary or metastatic malignant neoplasm that affects the colon or rectum. "MOB1 inhibits the malignant progression of colorectal cancer by decreasing PAK2 and thus influences the proliferation and migration of colorectal cancer." (PMID 39769207, 2024). "Recent research has revealed that MOB1 promotes the malignant progression of colorectal cancer via regulating PAK2." (PMID 39769207, 2024). "Our data reveal a unique dependency of mesenchymal CRC and provide a rationale for PAK2 inhibition to target this aggressive subgroup of colorectal cancer." (PMID 36869386, 2023). "LINC00858 regulated PAK2 signaling pathway through sponge adsorption of miR-4766-5p to promote the progression of colorectal cancer." (PMID 36248984, 2022). "Rescue experiment showed that over-expressed AZGP1 promoted the migration of colorectal cancer, but it can be reversed when the PAK2 inhibitors are added." (PMID 31632499, 2019). "In pancreatic and colorectal cancers, PAK2 interacts closely with the tumor microenvironment and cellular modulators like Mps one binder 1 (MOB1) and minichromosome maintenance complex component 7 (MCM7), emphasizing the need for context-specific therapeutic strategies." (PMID 39769207, 2024). "Moreover, a previous study reported that LINC00858 could mediate PAK2 by sponging miR-4766-5p, which facilitated colorectal cancer development." (PMID 35468892, 2022).
melanoma (7 papers, 2016 to 2025). A malignant, usually aggressive tumor composed of atypical, neoplastic melanocytes. "miR-107 promotes cell proliferation through the PAK2 pathway, whereas miR-137 suppresses melanoma cell proliferation by targeting PAK2." (PMID 39769207, 2024). "DOCK10 activates Cdc42 which in turn leads to phosphorylation of MLC2 by PAK2, driving the amoeboid phenotype in melanoma." (PMID 34196668, 2021). "In a previous study, two miRNAs were shown to directly target PAK2, and among these, miR-137 inhibited proliferation in melanoma cells." (PMID 29362401, 2018). "Of the other PAK isoforms, only PAK2 was found to be overexpressed in melanoma cell lines, compared to melanocytes." (PMID 27765920, 2016). "However, deletion of DOCK10, PAK2 or N-WASP, which all contribute to amoeboid migration in melanoma cells, also resulted in an elongated morphology, implicating more Cdc42 pathways in mesenchymal migration." (PMID 34196668, 2021). "This is not surprising given that PAK2 expression is already known to be overexpressed in melanoma cells and important in invasion." (PMID 27765920, 2016).
heart failure (6 papers, 2019 to 2024). Inability of the heart to pump blood at an adequate rate to meet tissue metabolic requirements. "Loss of Pak2 could then contribute to the pathogenesis of heart failure by promoting myocardium damage from defective ER stress response and enhancing Nrf2 maladaptive regulation of RAAS activation." (PMID 35350536, 2022). "However, during pressure overload or metabolic stress condition, loss of Pak2 in the heart impaired the activation of the ER stress response causing cardiomyocytes dysfunction and heart failure." (PMID 39899001, 2022). "PAK1 deficiency leads to cardiac hypertrophy and increased risk of mortality related to heart failure, and PAK1 or PAK2 activation may be beneficial in hypertrophy and heart failure." (PMID 30858169, 2019). "In the TAC mouse model, Pak2 overexpression was able to maintain ER homeostasis and protect against heart failure by inhibiting apoptosis and improving cardiac function." (PMID 39899001, 2022). "In human iPSC-derived cardiomyocytes, PAK2 (p21-activated kinase 2) activation can enhance ER function, reduce cell apoptosis, and protect from heart failure through the IRE1α/XBP1 (X-box binding protein 1)-dependent pathway." (PMID 33179756, 2020). "This indicates that modulating Pak2 could be a feasible approach for regulating cardiomyocyte proliferation at some extent used for heart failure treatment." (PMID 39899001, 2022). "Modulation of Pak2 activity may present as a promising novel therapeutic strategy for treating cardiac disease and heart failure." (PMID 30620686, 2019). "Pak2 activation is able to restore ER function, therefore ameliorating heart failure progression." (PMID 30620686, 2019). "Thus, Pak2 regulation of Nrf2 homeostasis may present as a potential therapeutic route to alleviate detrimental ER stress and heart failure." (PMID 35350536, 2022). "In our study, we found that PE elevated Pak2 expression in the peri‐infarct cortex post‐stroke, consistent with a study reporting that Pak2 enhances the IRE1/XBP1 branch of the UPR and thereby prevented heart failure." (PMID 39328024, 2024).
leukemia (6 papers, 2014 to 2025). A malignant (clonal) hematologic disorder, involving hematopoietic stem cells and characterized by the presence of primitive or atypical myeloid or lymphoid cells in the bone marrow and the blood. "Our results suggest that PAK2 is the most important member of PAK group I in leukemia cell adhesion to fibronectin." (PMID 33464167, 2021). "The band pattern obtained from leukemia cells was similar to that from adherent cells: PAK2 antibody recognizes a dominant band at 60 kDa, whereas PAK1 is detected in several bands in the range from 64 to 67 kDa." (PMID 33464167, 2021). "In murine fibroblasts and human leukemia cells, IR exposure activates p21-activated kinase 2 (Pak2, gamma-Pak)." (PMID 26269784, 2014). "Here, we studied the individual roles of PAK1 and PAK2 in BCR/ABL1+ leukaemia." (PMID 28707321, 2017). "In BCR/ABL1+ leukaemia, PAK1 and PAK2 are upstream regulators of the transcription factor STAT5 – a key node for initiation and maintenance of disease." (PMID 28707321, 2017). "In addition, PAK inhibition by IPA3 in leukemia cell lines significantly lowered OCR, revealing roles for PAK1 and PAK2 in the metabolic regulation of both mitochondrial respiration and aerobic glycolysis." (PMID 37759961, 2023). "We anticipate that pharmacological inhibitors of the identified targets, e.g. PAK2 and PTK2B/PYK2, may have great clinical potential as therapy for lymphoma and leukemia patients." (PMID 35440579, 2022). "In line with this hypothesis, reduction of PAK1, but not of PAK2 levels by means of shRNA was previously reported to inhibit cell proliferation in leukemia cell lines." (PMID 33464167, 2021).
cardiac hypertrophy (5 papers, 2019 to 2025). "Pak proteins are canonical effectors of Rac1 and cardiomyocyte-specific deletion of either Pak1 or Pak2 phenocopies exacerbated cardiac hypertrophy and dysfunction in response to pressure overload or AngII infusion that we observed in Rac1cKI mice." (PMID 40924486, 2025). "To investigate the therapeutic viability of Pak2 as a novel therapeutic target for cardiac hypertrophy and arrhythmias, we developed the small molecule Pak2 activator JB2019A." (PMID 40068092, 2025). "Consistent with our previous findings, overexpression of active Pak2 prevents the ER stress induced progression into cardiac hypertrophy and dysfunction." (PMID 35350536, 2022). "We first investigated potential protective effects of Pak2 signaling on ventricular arrhythmogenic tendency under conditions of acute isoproterenol induced cardiac adrenergic stress and chronic TAC induced ventricular hypertrophy." (PMID 40068092, 2025). "After 2 weeks of TAC, forced expression of XBP-1s relieved distressing ER stress responses in Pak2-CKO hearts, as well as showing reduced cardiac hypertrophy, improved cardiac performance, and less apoptosis (Online Figure XVID through XVIF)." (PMID 30620686, 2019).
head and neck cancer (5 papers, 2018 to 2023). A primary or metastatic malignant neoplasm affecting the head and neck. "Head and neck cancer: In head and neck cancer cells, PAK2 binds with c-Myc and stimulates c-Myc expression, resulting in high levels of PKM2 by binding to its promoter." (PMID 36830998, 2023). "Overexpression of p21-activated kinase 2 (PAK2) is frequently identified in head and neck cancers, with a positive correlation of PAK2 with worst outcomes in this type of cancer." (PMID 36568220, 2022). "PAK2-c-Myc- PKM2 is considered to have a key role in oncogenesis but also in radio-resistance of head and neck cancers via regulating Warburg effect." (PMID 36568220, 2022). "Differential expression levels of PAK2 have been reported in various malignancies including breast, gastric, hepatocarcinoma and head, and neck cancer." (PMID 32322560, 2020). "The present study highlights the undiscovered role of PAK2 in head and neck oncogenesis, wherein we showed that the elevated expression of PAK2 promotes head and neck cancer growth and provides chemotherapeutic resistance." (PMID 30068946, 2018). "In this study, we have analyzed the expression of HMs in microarray profiles of head and neck cancer (HNC), wherein a highly significant overexpression of p21-activated kinase 2 (PAK2) was identified which was further validated in HNC patients." (PMID 30068946, 2018). "Interestingly, the head and neck cancer showed a similar behavior of reduced migration and invasion upon PAK2 depletion, which established the fact that oncogenic activity of PAK2 is not cell type specific." (PMID 30068946, 2018).
lymphoma (4 papers, 2017 to 2022). A malignant (clonal) proliferation of B- lymphocytes or T- lymphocytes which involves the lymph nodes, bone marrow and/or extranodal sites. "PAK2‐deficient cells fail to form colonies in methylcellulose and to induce lymphomas in vivo." (PMID 28707321, 2017). "PAK2 phosphorylation and total protein levels were also up-regulated in Eμ-Myc/cRel−/− lymphoma cells." (PMID 36240067, 2022). "This subsequently led to the identification of enhanced levels of activity of the RAC pathway effector PAK2 activity in both the Eμ-Myc/RelAT505A and Eμ-Myc/c-Rel−/− lymphomas." (PMID 36240067, 2022). "In agreement, no significant change in PAK2 protein levels were observed in the proteomics dataset in the Eμ-Myc/RelAT505A lymphomas compared with WT cells; no phosphopeptides were observed for the region surrounding T402." (PMID 36240067, 2022). "Secondly, in our parallel paper, where we investigate the compensatory bypass pathways that become activated in c-Rel null and Eμ-Myc/RelaT505A lymphomas, we show that the RelA T505A lymphomas have increased sensitivity to drugs targeting the PI3K and PAK2 kinases." (PMID 36240065, 2022).
non-small cell lung carcinoma (4 papers, 2021 to 2025). A group of at least three distinct histological types of lung cancer, including non-small cell squamous cell carcinoma, adenocarcinoma, and large cell carcinoma. "Notably, inhibition of miR-7-5p can directly induce apoptosis via targeting P21-activated kinase 2 (PAK2) in non-small-cell lung cancer." (PMID 33456356, 2021). "Experiments have shown that the use of the PAK 2 inhibitor IPA-3 can effectively inhibit the migration and invasion of non-small-cell lung cancer cells, which provides a new idea for the treatment of this species." (PMID 40149657, 2025).
osteoarthritis (4 papers, 2019 to 2023). A noninflammatory degenerative joint disease occurring chiefly in older persons, characterized by degeneration of the articular cartilage, hypertrophy of bone at the margins and changes in the synovial membrane. "Downregulated miRNA-455-3p promoted TGF-β signaling and inhibited the development of osteoarthritis by targeting PAK2." (PMID 36694228, 2023). "However, it has been reported that miR-455-3p can promote TGFβ/SMAD signaling in chondrocytes and inhibit the development of osteoarthritis by directly targeting PAK2." (PMID 33708992, 2021). "Furthermore, many -3p miRNAs have important roles in physiology and pathophysiology, such as miR-455-3p which targets the 3′ UTR of PAK2 (P21-Activated Kinase 2), inhibiting the cartilage degeneration pathway in human osteoarthritis models both in in vitro and ex vivo experiments." (PMID 31952362, 2020).
Intellectual disability (3 papers, 2019 to 2023). "Noteworthily, 21 proteins are related to autism spectrum disorders (e.g. PAK2), intellectual disability (e.g. PAK1), neurodevelopmental disorders (e.g. GSK3β) and epileptic encephalopathies (e.g. MAP1B)." (PMID 37830910, 2023). "This deletion is different from the canonical region, as it does not include the PAK2 and DLG1 genes, considered as candidates for causing intellectual disability." (PMID 31338352, 2019).
meningioma (3 papers, 2015 to 2024). A generally slow growing tumor attached to the dura mater. "We found that Pak1 and Pak2 were much more abundant than Pak3 in both meningioma and arachnoidal cells, as determined by immunoblot." (PMID 25596744, 2015). "To investigate the significance of Pak1 and Pak2 in meningiomas, we used doxycycline-inducible short hairpin RNA (shRNA) to reduce Pak1 or Pak2 expression, respectively." (PMID 25596744, 2015). "Reduction of Pak1 expression had a greater effect than reduction of Pak2 expression, with no net increase in BLI signal over a five-week period, suggesting that, of these two enzymes, Pak1 has a dominant role in the growth of meningioma." (PMID 25596744, 2015).
pancreatitis (3 papers, 2021 to 2025). Inflammation of the pancreas. "Notably, they also showed that PAK2 is involved in pathophysiological events such as cell death and trypsin activation, which are implicated in the onset of pancreatitis." (PMID 39769207, 2024). "Together with evidence that inhibiting Rac1, an upstream activator of PAK, reduces the severity of pancreatitis, these results suggest that PAK2 may be a promising therapeutic target for addressing pancreatitis-related pathophysiology in pancreatic acinar cells." (PMID 39769207, 2024). "The studies of physiological/pathological function show that PAK2 and PAK4 are involved in secretory function and activating the central growth signaling cascade involving the MAPK cascade and that PAK2 activation plays an essential role in the induction of pancreatitis." (PMID 40001881, 2025).
retinal detachment (3 papers, 2023 to 2025). An eye emergency condition which may lead to blindness if left untreated. "This rare case report proposes a probable link between bilateral retinal detachment, chylothorax, and purpura fulminans in a neonate with a PAK2 genetic variant." (PMID 40262506, 2025). "As far as we are aware, this represents an uncommon case of bilateral retinal detachment in a neonate with congenital chylothorax and purpura fulminans, associated with a PAK2 genetic variant." (PMID 40262506, 2025). "Based on our case report and two other cases, we recognize that the combination of pleural effusions and retinal detachment in the presence of PAK2 genetic variant may suggest the diagnosis of Knobloch syndrome type 2." (PMID 40262506, 2025). "A potential relationship between bilateral retinal detachment, chylothorax, and purpura fulminans in a female neonate with a PAK2 gene variant is not commonly reported." (PMID 40262506, 2025).
schizophrenia (3 papers, 2013 to 2021). A major psychotic disorder characterized by abnormalities in the perception or expression of reality. "For instance, a rare chromosomal deletion including the PAK2 gene has recently been associated with schizophrenia." (PMID 23613712, 2013). "Our study supports the findings from the literature regarding the association of the PAK2, ARHGAP11B, and PRODH genes with schizophrenia and/or bipolar disorder." (PMID 33510659, 2020). "Our findings support the association of the PAK2, ARHGAP11B, and PRODH genes with schizophrenia and/or bipolar disorder." (PMID 33510659, 2020).